MALAT1 (metastasis associated lung adenocarcinoma transcript 1)
Diseases named in the same sentence as MALAT1 in open-access papers (continued):
Sharing a sentence is not in itself a finding about the gene and the disease.
diabetes (continued). "Future studies will be conducted to further elucidate the details of MALAT1 in different diabetes and EMT phases." (PMID 36827547, 2023). "MALAT1 is a highly conserved lncRNA playing an important role in diabetes progression by modulating genes at the transcription level." (PMID 36297381, 2022). "Different studies have shown that MALAT1 expression is increased in diabetes-related complications, including diabetic cardiomyopathy, diabetic kidney disease, diabetic retinopathy, and gestational diabetes." (PMID 35368523, 2022). "MALAT1 has been shown to play an important role in the pathophysiology of diabetes-related complications." (PMID 35163020, 2022). "MALAT1 has been reported to regulate endothelial cell function and vessel growth and to be involved in the endothelial dysfunction in diabetes mellitus." (PMID 34123418, 2021). "Currently, MALAT1 appears to be greatly relevant to diabetes and its function in DCM development and progression has drawn the attention of many scholars." (PMID 33889601, 2021). "MALAT1 expression has been found to be downregulated after exercise, and an important research has documented that MALAT1 participated in the protective effects of exercise against insulin resistance in type 2 diabetes mellitus." (PMID 34123418, 2021). "In another study, researchers reported that exercise reduced insulin resistance in type 2 diabetes mellitus via mediating the lncRNA MALAT1/microRNA-382-3p/resistin axis." (PMID 34284789, 2021). "MALAT1 is obviously an essential regulatory factor for ischemic reperfusion injury due to diabetes mellitus cerebrovascular diseases." (PMID 35058920, 2021). "Obviously, MALAT1 regulates diabetes-related retinal vessel function by activating ASK1/p38/NLRP3 signaling pathway." (PMID 35087834, 2021). "Long noncoding RNA MALAT1 is closely related to diabetes and kidney diseases and is expected to be a new target for the diagnosis and treatment of diabetic nephropathy." (PMID 32832561, 2020). "The protective role of MALAT1 delivered by exosomes is in contrast to the observed upregulation of cellular MALAT1 in various diabetes-related complications." (PMID 33023156, 2020). "Diabetes rats induced by streptozocin (STZ) presented severe pericytes loss, while knockdown of MALAT1 by GapmeRs can reverse the diabetes-induced pericytes loss." (PMID 32752143, 2020). "More recently, several studies have identified dysregulation of MALAT1 expression in multiple pathophysiological complications of diabetes including retinopathy, artherosclerosis, cerebrovascular disorder, renal disorders, etc.." (PMID 32503170, 2020). "LncRNA MALAT1 modulates inflammatory response in diabetes-initiated microvascular complications, such as DKD and diabetic retinopathy." (PMID 32832561, 2020). "Compelling studies have shown that MALAT1 is involved in some diseases, such as cardiovascular disease, diabetes-related complications, cancer, and metastasis, including OA." (PMID 33519887, 2020). "Given the diverse role of MALAT1 in cancer and other disease areas such as diabetes and inflammation, MALAT1 is being actively investigated as a potential therapeutic target using different modalities." (PMID 32503170, 2020). "MALAT1 is a 6.5-knt lncRNA, which was first found in lung adenocarcinoma, playing significant roles in the pathophysiological process of diabetes and diabetes-related complications by modulating gene transcription." (PMID 33274006, 2020). "This study aimed to explore the circulating expression level and significance of lncRNA Malat1 in patients with type 2 diabetes mellitus (T2DM) and diabetic kidney disease (DKD)." (PMID 32832561, 2020). "MALAT1 was previously reported to regulate Nrf2 to control the generation of ROS in diabetes and other ROS-induced diseases." (PMID 32972446, 2020).
diabetes (continued). "MALAT1, one lncRNA, is involved in several physiopathological process including angiogenesis, diabetes progression, tumour progression, cardiovascular remodelling 53 and tissue inflammation." (PMID 32812343, 2020). "Recently, intravitreal injection of MALAT1-siRNA in diabetes-induced mice reduced the functional and morphological damage of rods and cones, indicating its protective, likely indirect, effect against secondary PR loss." (PMID 33537317, 2020). "There is also evidence that serum levels of MALAT1 in patients with diabetes who smoked were significantly higher in comparison with nonsmokers patients." (PMID 32368256, 2020). "Taken together, our data indicates that the heightened production of MALAT1 promotes an inflammatory phenotype in diabetes." (PMID 31337130, 2019). "Nearly analogous to ANRIL, the reductions of MALAT1, through silencing or knockout strategies, significantly prevented diabetes-induced increases in EZH2, SUZ12, and EED RNA levels." (PMID 31337130, 2019). "MALAT1 is upregulated in many types of cancer, myocardial infarction, diabetes mellitus, and diabetic retinopathy." (PMID 31024342, 2019). "It has also been reported that Malat1 is involved in diabetes-induced microvascular dysfunction and regulates retinal endothelial cell proliferation, migration, and tube formation." (PMID 29891768, 2018). "MALAT1 was closely related to inflammatory reaction in a variety of pathological and physiological circumstances, including DR and diabetes-induced vascular complications." (PMID 29844328, 2018). "lncRNA MALAT1 was significantly increased in various models of diabetic mellitus, such as high glucose treated RF/6A cell, in the samples of aqueous humor, and in fibrovascular membranes of diabetic patients." (PMID 29915562, 2018). "MALAT1 is a large, infrequently spliced non-coding RNA, which was closely related to various pathological processes, such as cancer, diabetes complications, and innate immunity." (PMID 29764394, 2018). "Malat1 KO mice with STZ-induced diabetes and age-and sex-matched controls were monitored for 2 months." (PMID 29695738, 2018). "Two studies by Zhang and colleagues revealed that MALAT1 knockdown can reduce diabetes-induced myocardial inflammation as well as cardiomyocyte apoptosis, and consequently improve left ventricular function in diabetic rats." (PMID 29050364, 2017). "In our opinion, inhibition of MALAT1 expression as a potential anti-angiogenic therapy for diabetes-related microvascular complications merits further exploration." (PMID 28829354, 2017). "Previous studies demonstrated MALAT1 was significantly increased in high glucose‐treated retinal endothelial cells and in the retinas of diabetic mice 9, implying a role of MALAT1 in diabetes microvascular complication." (PMID 28444861, 2017). "Knockdown of MALAT1 significantly alleviates diabetes-induced microvascular dysfunction in vivo and inhibits endothelial cell proliferation, migration, and tube formation in vitro by changing the levels of phosphorylated p38 MAPKs." (PMID 27043545, 2016). "Together, these findings indicate that MALAT1 is a potential regulator of diabetes-induced microvascular complication." (PMID 25356875, 2014). "To gain the insight into the functional relevance of diabetes-induced MALAT1 upregulation, we estimated the effect of MALAT1 knockdown on endothelial cell viability in vitro." (PMID 25356875, 2014). "The results suggest that targeting exosomal MALAT1 may offer a novel and effective therapeutic approach for mitigating VC in metabolic disorders such as diabetes." (PMID 41440015, 2025). "A number of retinal LncRNAs including MALAT1, MIAT1, ANRIL, and CytB are also aberrantly expressed in diabetes, and are associated with the regulation of metabolic abnormalities implicated in the development of diabetic retinopathy including inflammation, oxidative stress and mitochondrial damage." (PMID 39558680, 2024).
diabetes (continued). "Macrophage-derived exosomal MALAT1 also exhibited crosstalk with diabetes-related complications." (PMID 39502508, 2024). "Recent studies have shown that MALAT1 expression is significantly elevated in the peripheral blood of patients with coronary artery disease; lncRNA MALAT1 gene expression is upregulated in patients with diabetes mellitus combined with coronary artery disease." (PMID 38439031, 2024). "Several retinal LncRNAs including LncRNAs MALAT1, MIAT1, ANRIL, and CytB are aberrantly expressed in diabetes and are associated with the metabolic abnormalities implicated in the development of diabetic retinopathy including inflammation, oxidative stress and mitochondrial damage." (PMID 39558680, 2024). "Interestingly, some herbal medicines have also been found to mitigate the progression of metabolic syndromes such as diabetes by modulating MALAT1 and related pathways." (PMID 39502508, 2024). "Thus, the objective ofthis study was to compare MALAT1 and TUG1expressions in urine of patients with type 1 diabetes mellitus (T1DM)categorized according to DKD presence." (PMID 37272835, 2023). "Inhibition of LncRNA MALAT1 alleviates diabetes-induced neurodegeneration." (PMID 35733767, 2022). "This suggests that macrophage-derived exosomes containing MALAT1 may serve as a novel cell-free approach for the treatment of vascular disease in diabetes mellitus." (PMID 35163020, 2022). "Studies showed that MALAT1 is involved in the pathogenesis of diabetes and types of cancers." (PMID 35368523, 2022). "Clearly, these studies demonstrated that MALAT1 played important roles in regulating hepatic insulin sensitivity, and inhibiting MALAT1 expression represents a potential therapeutic strategy for the treatment of IR and diabetes." (PMID 36555704, 2022). "lncRNA MALAT1 was highly expressed in endothelial cells in diabetes." (PMID 36474713, 2022). "Macrophage-derived exosomes containing MALAT1 may serve as a novel cell-free approach for the treatment of vascular disease in diabetes mellitus." (PMID 35163020, 2022). "MALAT1 can also play significant roles in pathophysiological processes, tissue inflammation, tumor progression, angiogenesis, cardiovascular remodeling, liver fibrosis, and diabetes progression by modulating gene transcription." (PMID 35058920, 2021). "In diabetic cataract, MALAT1 promote the apoptosis and oxidative stress of HLECs through the initiation of the p38MAPK signaling pathway, MALAT1 is considerably overexpressed in cardiac tissue of rats with diabetes, and its inhibition results in improvement in the cardiac function." (PMID 35058920, 2021). "The lncRNA MALAT1 was verified to up-regulate glucose causal inflammatory factors IL-6 and TNF-α, leading to the potential development of therapeutics targeting MALAT1 for diabetes related vascular complications." (PMID 32487016, 2020). "Previously, MALAT1 was however detectable in most diabetes mellitus patients, suggesting that diabetes mellitus may increase circulating Malat1 levels." (PMID 32764470, 2020). "Lnc-MALAT1 expression was elevated in diabetes compared to non-diabetes (P=0.017)." (PMID 33111743, 2020). "LncRNA Malat1 is highly expressed in DKD patients, and the combined detection of ACR, creatinine, α1-MG, and LncRNA Malat1 with diabetes mellitus may be the best way to diagnose diabetic nephropathy." (PMID 32832561, 2020). "Besides, it has also been reported that MALAT1 is involved in diabetes-induced microvascular dysfunction and regulates retinal endothelial cell proliferation, migration and tube formation." (PMID 32342982, 2020). "This indicates the upexpressed MALAT1 induced by diabetes might represent an important regulator of EC in DM and it can possibly act as a novel therapeutic target to lessen the burden that is induced by the vascular complication of ED-associated diabetes." (PMID 34968230, 2019).
diabetes (continued). "Indeed, in recent years, the importance of MALAT1 is being recognized by researchers in the field of diabetes and several functional studies are being carried out that specifically examine the dynamics of this lncRNA in diabetic complications." (PMID 31337130, 2019). "Interestingly, intraocular injections of a MALAT1 short hairpin RNA (shRNA) in the diabetic rats significantly alleviated diabetes-induced retinal inflammation, retinal cell apoptosis, vascular leakage, and electroretinogram abnormalities." (PMID 31337130, 2019). "Corresponding to our observed in vitro patterns, the genetic ablation of Malat1 (i.e., a global knockout) also diminished diabetes-induced vascular leakage and inflammation in the retinal tissues of Malat1 knockout diabetic mice compared to wild-type diabetic controls." (PMID 31337130, 2019). "Coinciding with our findings, several studies reported higher expression of MALAT1 in the kidney damage induced via different models including streptozotocin-induced diabetes, hypoxic induction, renal ischemia/reperfusion, and lipopolysaccharide-induced renal injury." (PMID 31684190, 2019). "Moreover, MALAT1 knockdown significantly alleviated diabetes-induced microvascular dysfunction in vivo and inhibited endothelial cell migration, tube formation and proliferation in vitro." (PMID 30988072, 2019). "In addition to the reduction in inflammation, echocardiographic analyses indicated that Malat1 KO attenuated diabetes-induced cardiac dysfunction." (PMID 30909482, 2019). "The expression of MALAT1, SAA3 and inflammatory mediators IL-6 and TNF-α were down-regulated after transfection of the MALAT1-specific siRNA, which may eventually promote diabetes-induced micro and macrovascular complications." (PMID 29050364, 2017). "Together, these studies suggest a role for MALAT1 in processes related to inflammation and hypoxia within the context of diabetes; additional work is necessary to further elucidate the role of this lncRNA in biological processes that underlie the development of renal dysfunction in T2D." (PMID 28829354, 2017). "Moreover, experimental evidence has shown that MALAT1 plays an important role in diabetes-induced retinal vessel dysfunction." (PMID 27043545, 2016). "Identification of such novel mechanism may lead to the development of RNA-based therapeutics targeting MALAT1 for diabetes-induced micro and macro vascular complications." (PMID 25787249, 2015). "Here, we investigated whether MALAT1 regulates inflammatory pathways involving inflammatory cytokines in diabetes." (PMID 25787249, 2015). "However, it is to be noted that the demonstrated role of MALAT1-SAA–Cytokine needs further evaluation in well-designed animal experiments with long-term diabetes." (PMID 25787249, 2015). "Further duration-dependent studies at various stages of diabetes using animal models (acute, short-term and long-term) would reveal whether this lncRNA, MALAT1 is a real culprit as an initiator of inflammation and oxidative stress." (PMID 25787249, 2015). "Inhibition of MALAT1 may serve as a novel therapeutic strategy for diabetes-related microvascular complications." (PMID 25356875, 2014). "Inhibition of MALAT1 may serve as a potential target for anti-angiogenic therapy for diabetes-related microvascular complications." (PMID 25356875, 2014). "Thus, the elevated MALAT1 levels in older patients with longer durations of diabetes might reflect cumulative inflammatory damage, potentially exacerbating cardiovascular complications." (PMID 40350526, 2025). "High glucose stimulation upregulates the expression level of MALAT1 and inhibits miR-150-5p expression in macrophages, counteracts the inhibitory effect of miR-150-5p on macrophage resistin expression, and promotes pathological progression of diabetes-related vascular disease." (PMID 39502508, 2024).
diabetes (continued). "Furthermore, increased expression of MALAT1 has been demonstrated in RF/6A hyperglycemic model cells and the aqueous humor and fibrovascular membranes of patients suffering from diabetic retinopathy, a common complication of diabetes." (PMID 38674413, 2024). "Hence, inhibition of MALAT1 may be a potential target for anti-angiogenic therapy of diabetes-related microvascular complications." (PMID 37322431, 2023). "However, in addition, Malat1 is dysregulated in the PodR231Q/A286V model (up at 4 weeks, down at 12 weeks) and may consequently play a role in podocyte biology beyond diabetes mellitus." (PMID 33804736, 2021). "Although several lncRNAs, including HILNC25, lncRNA MEG3, and MALAT-1, have been found to contribute to diabetes, little is known about the expression profiles of lncRNAs in T1DM patients and whether lncRNAs can be used as diagnostic or prognostic tool for T1DM." (PMID 32719778, 2020). "However, the amplitudes and outer nuclear layer were still significantly higher and thicker in the MALAT1-siRNA mice compared to diabetic control group, suggesting that silencing of MALAT1 shows protective effects on retinal photoreceptors and decreases retinal neurodegeneration due to diabetes." (PMID 33374507, 2020). "Furthermore, lnc-MALAT1 expression was elevated in AIS patients with diabetes." (PMID 33111743, 2020). "LncRNA Malat1 plays a role in multiple physiological processes, such as alternative splicing, nuclear organization, and epigenetic modulation of gene expression, and it is also closely related to various pathological processes ranging from diabetes complications to cancer." (PMID 31425535, 2019). "Interestingly, a recent study revealed that the involvement of MALAT-1 in diabetes-induced microvascular dysfunction, and inhibition of MALAT-1 may serve as a novel therapeutic strategy for diabetes-related microvascular complications." (PMID 25811929, 2015). "Univariate analysis showed that diabetic peripheral neuropathy, course of diabetes mellitus, FBG, 2hPG, lncRNA MALAT1, miR-199b and AGEs were significantly different among different groups (all P<0.05)." (PMID 41001679, 2025). "In the present study, we found that MALAT1 expression in the circulation of T2DM patients was positively correlated with age and diabetes duration." (PMID 40350526, 2025). "In conclusion, our study revealed the upregulation of the lncRNAs MALAT1,MEG3, and TUG1 in patients within the first five yearsof diagnosis of T1DM compared to controls and long-term diabetes group." (PMID 41123190, 2025). "It was reported that MALAT1 was highly expressed in diabetic kidney disease (DKD) patients and was upregulated in renal tissues of STZ-induced diabetes rats." (PMID 36760471, 2023). "For instance, MALAT1 enhanced the HG-induced cartilage endplate cell apoptosis by the p38/MAPK signaling pathway and CASC15 promoted diabetes-induced chronic renal failure and podocyte apoptosis." (PMID 34553078, 2021). "Using a streptozotocin (STZ)-induced diabetes animal model, recent studies from our laboratory have demonstrated that the lncRNAs ANRIL and MALAT1 have consequential roles in the pathogenesis of DCM." (PMID 30909482, 2019). "In order to compare the effects of miR-205-5p-depletion or MALAT1 overexpression in MSCs on their therapeutic potential in DF, the immunodeficient NOD/SCID mice received streptozotocin (STZ) to induce diabetes." (PMID 31866580, 2019). "We focused on miR‐181b and miR‐144 and lncRNAs MALAT1 and NEAT1 due to their potential relationship with diabetes." (PMID 28643459, 2017). "We further validated two ceRNA pairs (MALAT1‐miR‐144‐mTOR and NEAT1‐miR‐181b‐mTOR) involved in mTOR pathway and explored their significance in diabetes mellitus." (PMID 28643459, 2017). "The study analyzed the expression of lncRNA MALAT1 and NLRP3 in lower limb atherosclerotic disease in diabetes patients, explored the relationship between them and the disease, and whether lncRNA MALAT1 may be a new biomarker of LEAD." (PMID 38439031, 2024).